P4HB (prolyl 4-hydroxylase subunit beta)
Diseases named in the same sentence as P4HB in open-access papers (continued):
Sharing a sentence is not in itself a finding about the gene and the disease.
tumor (65 papers, 2010 to 2026). "P4HB promotes tumor growth and migration, making it a potential diagnostic and therapeutic target in CC58–60." (PMID 41315466, 2025). "Next, we analyzed the association between the circP4HB level and P4HB gene copy number in LUAD tumor tissues." (PMID 37880717, 2023). "We analyzed the correlations of P4HB expression with prognosis, clinical features, mutation genes, tumor heterogeneity, stemness, tumor immune microenvironment and PCa cells using multiple databases and in vitro experiment with R 3.6.3 software and its suitable packages." (PMID 37480146, 2023). "These analyses revealeda significant upregulation of ER chaperone mRNA expression in aHGGrelative to aLGG and aNNB that was associated with tumor aggressiveness and patientsurvival for HSPA5, HSP90B1, P4HB, and SERPINH1." (PMID 41287960, 2026). "VSIG4 was indicated to be a characteristic marker for tumor-associated macrophage populations, while TGFBI and P4HB were showed to be broadly expressed in ccRCC tumor and its immune microenvironment." (PMID 37035174, 2023). "In comparison to normal samples, UALCAN and GEPIA were used to confirm that tumor samples had increased P4HB expression." (PMID 37480146, 2023). "P4HB was significantly upregulated in tumor tissues compared to normal tissues and was closely related to biochemical recurrence-free survival." (PMID 37480146, 2023). "The qRT-PCR and immunohistochemistry (IHC) experiments were respectively conducted to evaluate the mRNA and protein expression levels of VSIG4, TGFBI, and P4HB in ccRCC thrombus-tumor-normal tissue triples." (PMID 37035174, 2023). "In the tumor samples, the expression of P4HB was significantly higher than the ductal clusters of adjacent normal samples." (PMID 37945567, 2023). "For tumor stemness, P4HB expression was positively related to EREG.EXPss and RNAss, but was negatively associated with ENHss and DNAss with statistical significance." (PMID 37480146, 2023). "The IHC assay further confirmed that protein expressions of VSIG4, TGFBI, and P4HB increased consecutively from normal kidney to renal tumor and then to tumor thrombus." (PMID 37035174, 2023). "Clinical correlations revealed that older age, a higher Gleason score, an advanced T stage, and residual tumour were all strongly correlated with increased P4HB expression." (PMID 37480146, 2023). "In the subgroup survival study, higher P4HB expression was associated with a reduced probability of BCR in terms of N0 stage, White population, residual tumor, age < 60, and overlapping or multiple zones than lower P4HB expression." (PMID 37480146, 2023). "In terms of clinical correlations, we found that higher P4HB expression was significantly related to older age, higher Gleason score, advanced T stage and residual tumor." (PMID 37480146, 2023). "Current studies have shown that P4HB is overexpressed in all kinds of tumor cells and is an important indicator to detect the tumor progression level." (PMID 36138770, 2022). "ECA pull-down followed by mass spectrometry further showed that there was significantly less expression of ECA binding membrane catalase (CAT) and prolyl 4-hydroxylase beta polypeptide (P4HB) in HCC tissues compared with the adjacent non-tumor tissues." (PMID 35392238, 2022). "Consistent with the results from HCC cell lines, the total membrane CAT and P4HB expression were higher in HCC tissues compared with adjacent non-tumor tissues." (PMID 35392238, 2022). "Hurst found that, as a new inhibitor, E64FC26 improved viability and limited the unfolded protein response, decreased global P4HB expression in normal healthy T cells, and reshaped T cell metabolism, which helps to enhance anti-tumor immune responses." (PMID 34620162, 2021). "Statistical analyses showed that P4HB expression level had significant correlation with tumour differentiation of ESCC (P = 0.016)." (PMID 33732415, 2021).
tumor (continued). "Our work provided novel findings that aberrant expression of P4HB promotes tumour invasion, angiogenesis and growth via the MAPK signaling pathways." (PMID 29069756, 2017). "In colon cancer, the expression of P4HB was higher in tumor tissue compared to normal tissue." (PMID 38029391, 2023). "Furthermore, the average expression level of P4HB in ccRCC tumor and renal epithelium was the highest among 31 single-cell clusters." (PMID 37035174, 2023). "The influence of MAP1B and P4HB in tumor immune infiltration cannot be ignored." (PMID 35954405, 2022). "P4HB is an endoplasmic reticulum chaperone protein with overexpression in numerous tumor tissues." (PMID 35436915, 2022). "Moreover, the expression levels of P4HB were upregulated in ESCC cell lines and ESCC tissues compared to adjacent normal tissues, and P4HB overexpression was correlated with poor survival and tumour differentiation of patients with ESCC." (PMID 33732415, 2021). "Moreover, P4HB, PDIA3, and PDIA4 were found to be up-regulated in ovarian cancer and associated with the tumor grade and poor prognosis." (PMID 32023222, 2020). "In this study, we determined P4HB levels in tumor and adjacent normal tissues of HCC patients." (PMID 28052026, 2017). "Furthermore, P4HB upregulation conferred malignant characteristics including proliferation, invasion, migration and angiogenesis in vitro, and increased tumor growth in vivo via the mitogen-activated protein kinase (MAPK) signaling pathway." (PMID 29069756, 2017). "The findings suggested that P4HB may regulate a wide range of gene functions but predominantly in angiogenesis and Tumour regulation." (PMID 29069756, 2017). "Among the risky genes, CTNNA1, P4HB, and LMAN2 are associated with tumor development." (PMID 24871302, 2014). "However, P4HB is predominantly expressed in acinar cells in normal tissues, with significantly lower expression levels observed in pancreatic ductal cells compared to tumor tissues." (PMID 38685045, 2024). "Functionally, COL10A1 contributes to ECM remodeling and can interact with proteins such as prolyl 4-hydroxylase subunit beta (P4HB) and integrin subunit beta 1 (ITGB1) to facilitate tumor cell proliferation and metastasis." (PMID 40826474, 2025). "We compared the expression levels of IGF2BP3, P4HB, RAC3 and CLK2 in TCGA BCa tissues and normal tissues, and the results showed that all four genes were significantly upregulated in tumor tissues." (PMID 38299148, 2023). "As we can see, the macrophage-expressed VSIG4 in lymph node was higher than that in ccRCC tumor and adjacent normal kidney, whereas the epithelium-expressed TGFBI and P4HB in ccRCC tumor were higher than those in adjacent normal kidney." (PMID 37035174, 2023). "Subsequently, we collected several clinical GBM tumor tissues and detected the expression levels of HLA-DMA, P4HB and RCN1 in GBM via qRT-PCR and IHC assays." (PMID 35436915, 2022). "We examined the basal protein level of P4HB in C2C12 myoblasts and other tumour cells, indicating that P4HB was expressed in normal C2C12 myoblasts, in which the level of P4HB was lower than that in YES2 cells." (PMID 33732415, 2021). "To elucidate the relevance of P4HB and RGS19 with respect to tumor progression, we further performed a subgroup analysis of multiple BUC clinicopathological features." (PMID 32903592, 2020). "In the current study, we also found that P4HB promotes HCC cell growth, migration, and invasion in vitro and tumor formation in vivo." (PMID 28052026, 2017). "P4HB was not expressed in any of the primary tumours of patients that had severe mesenteric fibrosis, but it was expressed in both the tumour cell cytosol and the surrounding stromal cells in some of the mesenteric metastases." (PMID 40998421, 2025). "For tumor heterogeneity, P4HB expression was positively related to MATH, but was negatively associated with tumor ploidy and microsatellite instability." (PMID 37480146, 2023).
tumor (continued). "Based on these findings, investigating the role of these interactions among P4HB, PDIA4 and PDIA6 in driving aggressive tumor phenotypes, such as proliferation, invasion and metastasis, could uncover potential targets for anti-metastatic therapies." (PMID 38029391, 2023). "We also found much lower expression levels of ECA-binding-membrane CAT and P4HB in HCC tumor tissues than adjacent non-tumor tissues from three HCC patients." (PMID 35392238, 2022). "To find out whether P4HB is dyregulated in HCC, we determined P4HB mRNA and protein levels in tumor and adjacent normal liver tissues of HCC patients by qRT-PCR and western blotting, respectively." (PMID 28052026, 2017). "Conversely, inhibiting MAPK pathway with U0126 abrogated the induction of VEGF, tumor invasion and angiogenesis, without alterations in P4HB protein levels." (PMID 29069756, 2017). "The myofibroblasts within the tumor were not a homogeneous population: some expressed only P4Hβ, αSMA, or SM22α; others expressed more than a single marker." (PMID 22848627, 2012). "Urinary detectable TGFBI and P4HB, but not VSIG4, were demonstrated to be higher expressed in patients with III-IV grade tumor than those with I-II grade tumor." (PMID 37035174, 2023). "We also identified six proteins (CALR, HIST2H2AC, HSPA5, P4HB, and PDIA6) in the HPA database that showed increased immunostaining in PCa tumor tissue, while low or not detected in normal prostate tissue." (PMID 33049715, 2020).
infection (9 papers, 2014 to 2025). The state of being infected such as from the introduction of a foreign agent such as serum, vaccine, antigenic substance or organism. "Other genes that increased infection efficiency by ≥4-fold upon knockout included MOSPD2, P4HB, and LY6E (each leading to an approximately 4-fold increase) and IRX2 (an approximately 8-fold increase)." (PMID 40901862, 2025). "To obtain additional evidence of the involvement of ERp57 in the interaction between Burkholderia and epithelial cells, we have carried out infection experiments in 9HTEo- cells transfected with short interfering RNA (siRNA) for ERp57, P4HB or with a negative control siRNA." (PMID 26879174, 2016).
heart disease (1 paper, 2025). "Additionally, protein disulfide-isomerase (P4HB) lactylation also has been identified as a new target of radiation-induced heart disease." (PMID 40849305, 2025).
kidney diseases (1 paper, 2022). "Hence, evidence suggests that P4HB might be a key biomarker and therapeutic target for human kidney diseases." (PMID 36226178, 2022).
skeletal dysplasia (1 paper, 2023). Any Mendelian diseases that affects growth and development of the skeleton. "Notably, mutations in SUCO and P4HB have been linked to skeletal dysplasia in humans, which aligns with the TAPT1 loss‐of‐function clinical presentation." (PMID 36652330, 2023).
P4HB also shares sentences with these, for which no sentence is quoted: atherosclerosis (5 papers); cardiovascular disease (5); malaria (5); metabolic syndrome (5); neuroblastoma (4); amyotrophic lateral sclerosis (3); neurodegenerative disease (3); ovarian tumor (3); Parkinson disease (3); renal cell carcinoma (3); adenocarcinoma (2); Alzheimer disease (2); colorectal cancer (2); endometrial carcinoma (2); esophageal cancer (2); hyperhomocysteinemia (2); Insulin resistance (2); myeloma (2); oesophageal cancer (2); prion disease (2); status epilepticus (2); Type 1 Diabetes (2); viral infection (2); adenocarcinoma of the esophagus (1); antiphospholipid syndrome (1); aortic aneurysm (1); autoimmune disease (1); Azoospermia (1); brain cancer (1); brain ischemia (1).
A further 51 diseases each share a sentence with P4HB in 1 paper.